RNU6-1261P (RNA, U6 small nuclear 1261, pseudogene)
Gene: Small nuclear RNA gene on chromosome 14 (34,675,891 to 34,675,994, forward strand). Ensembl gene ENSG00000253003.
Homologues: Orthologues: chimpanzee U6 (99% identical), macaque U6 (91% identical), rat U6 (74% identical), dog U6 (68% identical), mouse Gm26257 (65% identical). Paralogues in human: RNU6-28P (81% identical), RNU6-97P (81% identical), RNU6-1105P (80% identical), RNU6-822P (80% identical), RNU6-11P (79% identical), RNU6-21P (79% identical), RNU6-37P (79% identical), RNU6-43P (79% identical), RNU6-642P (79% identical), RNU6-774P (79% identical), RNU6-1164P (78% identical), RNU6-263P (78% identical), and 1288 more.